GOLPH3 (golgi phosphoprotein 3)
Diseases named in the same sentence as GOLPH3 in open-access papers (continued):
Sharing a sentence is not in itself a finding about the gene and the disease.
tumor (continued). "The tumor volume in the GOLPH3 siRNA#1 group starting from day 25 to the end of the experiment was significantly smaller than in the PBS and control siRNA groups (P < 0.05)." (PMID 26375441, 2015). "Similar to a previous study in castration-resistant PC, GOLPH3 expression was positively correlated with Gleason score, tumor stage and lymph node metastasis." (PMID 28983350, 2015). "Compared to patients with moderate/intense GOLPH3 expression, the patients whose tumor cells showed weak expression of GOLPH3 had significantly better outcomes in OS (P < 0.001)." (PMID 28983350, 2015). "GOLPH3 promotes cell transformation and tumor growth by activating mammalian target of rapamycin (mTOR-YB-1) signaling pathway." (PMID 28983350, 2015). "Strikingly, we found that the areas in T24 xenograft tumor specimens displaying high levels of GOLPH3 staining demonstrated strong Ki67 staining signals, and areas with low GOLPH3 expression had weakly detectable Ki67 expression." (PMID 26375441, 2015). "Depletion of GOLPH3 with small interfering RNA (siRNA) was found to suppress the transformation, proliferation and clonogenic growth in tumor cell lines." (PMID 25104140, 2014). "The Cox proportional hazards model indicated that the expression level of GOLPH3 protein, N classification and tumor resectability were all independent prognostic factors for poor overall survival in patients with PDAC." (PMID 25104140, 2014). "Recent studies have shown that overexpression of mammalian Vps74p and GOLPH3 results in cell transformation, tumor growth in vivo, and rapamycin hypersensitivity." (PMID 24019977, 2013). "A recapitulation of our results: firstly, a notably higher level of GOLPH3 expression was present in all tumor cell lines at both mRNA and protein levels, while bare expression of GOLPH3 was detected in normal human esophageal cells." (PMID 23056210, 2012). "Recent functional, cell biological, and biochemical analyses have shown that GOLPH3 can induce cell transformation and tumor growth by enhancing the activity of the mammalian target of rapamycin complex (mTORC)." (PMID 23056210, 2012). "GOLPH3 expression showed barely detectable in normal human esophageal cells, whereas a notably higher level of GOLPH3 expression was found in all tumor cell lines at both the mRNA and protein levels." (PMID 23056210, 2012). "Xenograft experiments revealed that tumor cells overexpressing GOLPH3 have an increased sensitivity to the mTORC1 inhibitor, rapamycin, and GOLPH3-dependent oncogenesis is associated with increased mTOR signaling." (PMID 22905766, 2012). "In xenograft experiments conducted in immunodeficient mice, tumor cells with overexpressed GOLPH3 showed increased sensitivity to therapy with the TORC1 inhibitor, rapamycin." (PMID 23056210, 2012). "The average expression level of GOLPH3 increased progressively through tumor stages I to IV, and levels were significantly higher than those in normal esophageal tissue." (PMID 23056210, 2012). "Compared to patients with intense or moderate GOLPH3 expression, the patients whose tumor cells showed weak expression of GOLPH3 had significantly better outcomes in terms of DFS (P<0.001)." (PMID 23006319, 2012). "Recent studies have reproted that GOLPH3 works as an oncoprotein promoting cell transformation and tumor growth by enhancing the activity of mTOR." (PMID 23006319, 2012). "Deletion of GOLPH3 and its closely related paralog GOLPH3L from cell lines results in extensive defects in glycosylation, and GOLPH3 is found to be frequently amplified in some solid tumor types, consistent with the known role of glycans in regulating immune responses to tumor cells." (PMID 41042862, 2025). "Targeted therapies disrupting mitochondrial function and inhibiting GOLPH3 could significantly affect the secretory pathway and potentially enhance an anti-tumor immune response." (PMID 38391929, 2024). "At the same time, GOLPH3 also participate in tumor angiogenesis and promote its rapid growth." (PMID 36967990, 2023).
tumor (continued). "Hypotheses suggest that chronic inflammation related to HCV infection, which can eventually lead to HCC, could use GOLPH3 as a mechanism for tumor formation." (PMID 37508488, 2023). "All these studies indicate that GOLPH3 can serve as a potential target in clinical tumor therapy." (PMID 36358544, 2022). "Previous studies have shown that STK25 could suppress tumor cell growth and proliferation by downregulating the Golph3-dependent mTOR pathway, promoting tumor cell apoptosis by regulating CCM2TrkA, etc.." (PMID 35756606, 2022). "Moreover, the average tumor volume and weight were significantly smaller in GOLPH3 knockdown plus sorafenib-treated group compared with that of the control group." (PMID 35073936, 2022). "Notably, the tumor growth and angiogenesis were further decreased in cells with GOLPH3 knockdown and treated with sorafenib." (PMID 35073936, 2022). "Moreover, patients with poor tumor differentiation and late staging had higher serum GOLPH3 concentrations." (PMID 33680216, 2021). "Hence, miRNA-3135b is a tumour suppressor regulating mTORC1 signalling via GOLPH3-mediated changes in Golgi architecture." (PMID 34195689, 2021). "Overall, our findings indicate that serum GOLPH3 may reflect the depth of tumor invasion and correlate with lymph node and distant metastases." (PMID 33680216, 2021). "A different group of evidence suggests that this myosin scaffold may contribute to tumor development and metastasis by regulating activity of its major binding partner, Golgi phosphoprotein 3 (GOLPH3)." (PMID 33670106, 2021). "Furthermore, IHC analysis showed high expression of GOLPH3, CD133, and ZEB1 in the tumor tissues formed by A549-GOLPH3 cells." (PMID 34671013, 2021). "In this study, we investigated whether GOLPH3 can be used as a tumor marker for early diagnosis and prognosis in patients with GC and CRC." (PMID 33680216, 2021). "GOLPH3 can regulate the function of Golgi protein glycosyltransferase, leading to the abnormal secretion of glycosylated protein, which can affect the growth, adhesion, migration, invasion and immunity of tumor cells." (PMID 34807928, 2021). "Moreover, GOLPH3 protein expression levels were significantly higher in the NSCLC tissues compared with those in the tumor-adjacent lung tissues." (PMID 34671013, 2021). "Several proteins interact with GOLPH3 to regulate downstream targets for tumor progression." (PMID 33134174, 2020). "Our data suggest that miR-3135b is a novel tumor suppressor with a potential role in the regulation of the GOLPH3/AKT1/mTOR axis to maintain Golgi integrity, which adds a piece in the puzzle of the novel cytoplasmic DNA damage response to DNA-damaging agents in CRC cells." (PMID 32601379, 2020). "Additionally, this study also confirmed SOX8 effects on enhancing tumor progression and growth in vivo, and GOLPH3 participated in the biological process of SOX8 in TSCC." (PMID 32307911, 2020). "Additionally, shRNA-transfected BXPC3 cells were transplanted into nude mice to investigate the effect of GOLPH3 on tumor growth in vivo." (PMID 33134174, 2020). "In this report, we focused on novel proteins that interact with GOLPH3, which might play important roles in the tumor growth and development of PDAC." (PMID 33134174, 2020). "Increasing evidence suggests that hTERT affects tumor cell proliferation; therefore, we examined whether the GOLPH3 expression level and relative telomerase activity affected the proliferation in PDAC cells." (PMID 33134174, 2020). "Finally, our study confirms high SOX8 expression in TSCC tumor tissues compared with that in adjacent non‐tumor counterparts, which shows positive correlation with GOLPH3 over‐expression and poor survival." (PMID 32307911, 2020). "In addition, a more in-depth investigation is needed to screen small molecules as anti-tumor drugs to inhibit the intracellular interaction of GOLPH3 and STIP1 in PDAC." (PMID 33134174, 2020).
tumor (continued). "Moreover, GOLPH3 up-regulation was shown to significantly enhance mouse xenograft tumor growth in vivo." (PMID 32023813, 2020). "This idea was supported by preclinical treatment studies showing that GOLPH3-expressing tumors are much more sensitive to mTOR inhibitors, raising the possibility that GOLPH3 levels might predict rapamycin efficacy in tumor therapy." (PMID 32023813, 2020). "Collectively, these results indicated that SOX8 promoted TSCC tumor growth via GOLPH3." (PMID 32307911, 2020). "Notably, we surprisingly found that, after gefitinib treatment, the tumour derived from GOLPH3 over‐expression cells significantly shrank and almost disappeared." (PMID 31094020, 2019). "The overall OR was 1.97 (95% CI = 1.34-2.88, p= 0.002) via a fixed effects model analysis (I2 = 40.0%, p = 0.139), suggesting that expression level of GOLPH3 was relatively higher in moderate and poor differentiation of tumor than that in well tumor differentiation." (PMID 31737112, 2019). "This suggests the possibility that in some tumor cells the levels of GOLPH3 could regulate a transition between a less active mesenchymal motility to a more amoeboid malignant behavior." (PMID 30779783, 2019). "In addition, the resistance consequent to the recovery from DNA damage given by GOLPH3 over-expression has specific relevance to tumor cells, as most standard therapeutic procedures include DNA damaging agents." (PMID 31557970, 2019). "In addition, eight studies 11, 16, 24-29 revealed the correlation between the GOLPH3 expression and tumor size." (PMID 31737112, 2019). "Interestingly, GOLPH3 over‐expression group exhibited higher sensitivity to gefitinib treatment, elucidated by the most striking tumour volume decrease." (PMID 31094020, 2019). "Therefore, our findings indicate that GOLPH3 enhances the tumour suppression effect of gefitinib on U251 and U87 cells." (PMID 31094020, 2019). "What’s more, knockdown GOLPH3 expression led to tumor growth restriction in xenograft tumor model." (PMID 29914442, 2018). "This study demonstrated that GOLPH3 was significantly over-expressed in human HCC tumor tissues." (PMID 29914442, 2018). "Fourthly, xenograft tumor model was used to study the function of GOLPH3 in tumor growth in vivo." (PMID 29914442, 2018). "In this study, we also discovered that GOLPH3 was high expressed in the HCC tumor tissues." (PMID 29914442, 2018). "In addition, IHC staining indicated that both the percentage of Ki67-positive cells and MVD were decreased in GOLPH3 knockdown tumors, which indicated that down-regulation of GOLPH3 inhibited tumor cells proliferation and tumor progression in vivo." (PMID 29914442, 2018). "It is reported that GOLPH3 can promote tumor growth via activating mTOR signaling pathway." (PMID 29914442, 2018). "Recent studies have demonstrated that GOLPH3 is an oncogene involved in the development and progression of several tumor types including lung cancer, breast cancer, melanoma, colon cancer, bladder cancer, gastric cancer, prostate cancer, oral tongue cancer, rhabdomyosarcoma, glioma and so on." (PMID 29914442, 2018). "GOLPH3 expression was highly correlated with tumor invasion depth (p=0.033)." (PMID 29285241, 2017). "Interestingly, low GOLPH3 expression tended to yield high sensitivity to nCRT: among the 71 patients with low expression, 44 cases showed tumor down-staging; meanwhile, 33 of the 77 cases with high expression showed down-staging (P = 0.020)." (PMID 27634904, 2016). "As a corollary, GOLPH3 could be mediating several specific functions in different tumor cells, yet little is known about the precise molecular mechanisms and the contribution of these functions to tumorigenesis." (PMID 27123979, 2016). "Tumor cells overexpressing GOLPH3 are more sensitive to rapamycin." (PMID 28983350, 2015).
tumor (continued). "Furthermore, GOLPH3 siRNA#1 resulted in a significant decrease in tumor volume and weight as measured at the end of the experiment at day 45 compared with control siRNA (P < 0.001)." (PMID 26375441, 2015). "In vivo studies further demonstrate that GOLPH3 silencing dramatically inhibits xenograft tumor growth and may be a promising therapeutic target." (PMID 26375441, 2015). "Importantly, the ability of GOLPH3 to modulate rapamycin-induced tumor cell death identifies it as a potential positive predictor of rapamycin sensitivity in tumor therapy." (PMID 24444035, 2014). "Furthermore, the immunohistochemical staining patterns revealed that GOLPH3 was mainly localized in the cytoplasm of the tumor cells." (PMID 25104140, 2014). "Therefore, targeting GOLPH3 may reduce mitochondrial oxygen consumption, a key factor in tumor hypoxia, as well as reduce PD-L1 functionality." (PMID 38391929, 2024). "Additionally, the in vivo biodistribution studies demonstrated that the angiotensin-cationic liposomes efficiently crossed the BBB, delivered GOLPH3-siRNA at the tumor site, and enhanced overall survival by inhibiting the tumor growth in tumor-bearing nude mice." (PMID 39457052, 2024). "Therefore, all three of these genes could be potentially good candidates for further study, especially GOLPH3 and COL5A1, whose expressions were found to be associated with tumor progression in other tumor types." (PMID 38173042, 2024). "Thus, GOLPH3 is believed to have the potential to change the tumor microenvironment." (PMID 36358544, 2022). "Combined detection of GOLPH3, CEA, and CA19-9 may be used as a new diagnostic method and an index to evaluate the surgical effect after radical surgery, and GOLPH3 may be used as a novel tumor marker for GC and CRC." (PMID 33680216, 2021). "Based on these findings, we hypothesized that GOLPH3 associated with STIP1 might regulate hTERT and telomerase activity via c-Myc, and then regulate cyclin D1 to promote the division and proliferation of tumor cells." (PMID 33134174, 2020). "In addition, GOLPH3 is considered as the new candidate target of many tumor therapies." (PMID 32307911, 2020). "Besides its effects on tumor growth and its action in enhancing oncogene function, GOLPH3 may also act on oncosuppressors." (PMID 32023813, 2020). "Likewise, the effects that the levels of GOLPH3 have on metalloproteinases in different types of tumor cell lines could be related to GOLPH3 promoting their secretory trafficking, resulting in enhanced extracellular matrix degradation." (PMID 30779783, 2019). "Importantly, GOLPH3 enhanced the anti‐tumour effect of gefitinib in vivo." (PMID 31094020, 2019). "In addition, because in the same tumor types the high expression of GOLPH3 is correlated with poor survival, it has been suggested that the levels of GOLPH3 could be used as biomarker of tumor progression." (PMID 27123979, 2016). "Importantly, the correlation between 5p13 copy number and increased phosphorylation of the p70 S6 kinase mTOR substrate in NSCLC tumor specimens links GOLPH3 function to mTOR activation and indicates that GOLPH3 tumorigenesis may be mediated by mTOR signaling." (PMID 22905766, 2012). "As reviewed earlier in proteins of the TGN, GOLPH3 was shown to recruit prohibitin-2 and LC3-II to promote autophagy and tumour progression." (PMID 40293576, 2025). "GOLPH3 affected EGFR recycling and post-translational modifications and promoted tumour growth by triggering autophagy." (PMID 40293576, 2025). "Co-immunoprecipitation showed that GOLPH3 acted as a scaffold to recruit LC3-II and prohibitin-2 to trigger autophagy and tumour progression." (PMID 40293576, 2025). "If PI4P is increased in the trans Golgi regions, PI4P-binding proteins like GOLPH3 and PITPNC1 are over-recruited, leading to malignant secretion that can develop angiogenesis, tumor invasion, and metastasis." (PMID 39675715, 2025).
tumor (continued). "In our study, we identified that GOLPH3 can be modulated by the BPA/GPER axis, which partly elucidates the impact of BPA and GPER on the tumor microenvironment." (PMID 38828452, 2024). "LINC01194 serves as a tumor promotor, and enhances progression of PCa by regulating LINC01194/miR-486-5p/GOLPH3 axis." (PMID 37025585, 2023). "Previously, we reported that GOLPH3 interacted with STIP1, which then regulated telomerase activity and promoted tumor progression in pancreatic ductal adenocarcinama." (PMID 35372504, 2022). "Concentrations of GOLPH3 in the sera of GC and CRC patients were related to tumor size, tumor invasion depth, cell differentiation, lymph node metastasis, and distant metastasis." (PMID 33680216, 2021). "Serum GOLPH3 concentrations were increased in GC and CRC patients with tumors greater than 5 cm, poor differentiation, greater depth of tumor invasion, and increased lymphatic and distant metastases (P < 0.05)." (PMID 33680216, 2021). "Golgi phosphoprotein 3 (GOLPH3) is an oncogene that has been shown to be involved with tumorigenesis in PCa and other neoplasms, and regulates (along with other trans-Golgi matrix family proteins) rapamycin signaling." (PMID 33562508, 2021). "To conclude, our study provided the first demonstration that miR-3150b exerted a tumor-suppressive role in HCC, at least in part, by targeting GOLPH3." (PMID 31806673, 2020). "Further insights into the relation between GOLPH3 and EGFR in tumor progression came from the study of Wu and co-workers." (PMID 32023813, 2020). "Patients with high GOLPH3 expression had poor DFS and OS in every molecular subtype, and an increase in tumor invasion and lymph node metastasis." (PMID 29285241, 2017). "Therefore, GOLPH3 could be used as an efficient target for tumor therapy." (PMID 27634904, 2016). "In this study, we found that GOLPH3 expression was upregulated in PDAC tissues at both the mRNA and protein level compared to adjacent non-tumor tissues." (PMID 25104140, 2014). "Clinical stage, GOLPH3 expression, TNM classification, histological differentiation, tumor location, therapy, completeness of surgical resection and complications were analyzed using univariable and multivariable Cox regression analyses." (PMID 23056210, 2012). "Furthermore, the positive correlation between GOLPH3 and USP44 in tumor samples also decreases substantially." (PMID 40136480, 2025). "GOLPH3 emerged from the TGN and was involved in the retrograde trafficking of cargo and thereby could affect tumour signalling." (PMID 40293576, 2025). "While GOLPH3 has been recently involved in regulation of autophagy in human cultured cells and in a few tumor contexts, its role in the process is not understood." (PMID 36435842, 2022). "Moreover, suppression of GOLPH3 expression using shRNAs in PANC1 and BXPC3 cells inhibited tumor cell proliferation both in vitro and in vivo." (PMID 33134174, 2020). "Also, effects of GOLPH3 knockdown and SOX8 over‐expression on Ki67 (a vital factor indicating tumor growth) expression in xenografts was investigated." (PMID 32307911, 2020). "In addition, our results further indicated that GOLPH3 expression correlated positively with STIP1 expression in PDAC tissues, and their co-localization in tumor cells implied their interaction." (PMID 33134174, 2020). "Our results showed that GOLPH3, acting as an oncoprotein, interacted with STIP1 to regulate telomerase activity and promote tumor progression, which might provide a new therapeutic target for PDAC." (PMID 33134174, 2020). "What’s more, by knocking down the GOLPH3 expression in HCC cells, the expression of p-mTOR (Ser2448), p-Akt (Ser473) and p-S6 K1 (Thr389) were remarkably decreased in the HCC cell lines and in the xenograft tumor model." (PMID 29914442, 2018). "Given that chemoresistant tumor cells have an EMT phenotype 43, whether GOLPH3 regulates chemoresistance in EOC needs to be investigated in further studies." (PMID 28332316, 2017).